NLRP3 (NLR family pyrin domain containing 3)
Diseases named in the same sentence as NLRP3 in open-access papers (continued):
Sharing a sentence is not in itself a finding about the gene and the disease.
Obesity (continued). "Thus, even though there was no cardiac inflammation, there was an NLRP3-dependent systemic inflammatory response to obesity." (PMID 31379826, 2019). "Notably, on control diet both Nlrp3−/− and Asc−/−(Pycard−/−) mice had reduced e′ compared to WT, but obesity did not affect e′ in these mice." (PMID 31379826, 2019). "Indeed, mice lacking Nlrp3 were resistant to the development of high fat diet-induced obesity and were also protected from obesity-induced insulin resistance." (PMID 30619282, 2018). "NLRP2 appears dysregulated in astrocytes, and NLRP3 in microglia in the context of Alzheimer’s disease as well as in other neurological diseases like Parkinson’s disease; additionally, NLRP2/3 are altered in pathologies that show comorbidity with AD: obesity, type-2 diabetes." (PMID 29078805, 2017). "Furthermore, NLRP3 inflammsome could be activated by saturated fatty acid, ceramides, modified LDL, and hyperglycemia in obesity and type 2 diabetes." (PMID 28790925, 2017). "In addition, HFD‐NLRP3−/− mice displayed a reduction in active caspase‐1 expression as well as in circulating and colonic IL‐1β levels, thus confirming previous evidence describing the involvement of NLRP3 inflammasome in the pathophysiology of obesity and related inflammation." (PMID 39287080, 2025). "However, some have reported contrasting results, with deficiency in NLRP3 and caspase-1 not protecting mice from HFD-induced obesity, which suggests that the presence of the NLRP3 and caspase-1 genes is not required for HFD-induced adipose tissue inflammation and glucose intolerance." (PMID 36065376, 2022). "Specifically, Vandanmagsar and collaborators described increased mRNA expression of NLRP3 and IL-1β (but not ASC) in AT from patients with obesity and T2D, and these levels correlated with glycemic state." (PMID 37819510, 2023). "A very recent work demonstrated that the absence of these three critical inflammasome components, Nlrp3, ASC, and caspase-1, in mice protects mice from HFD-induced obesity, insulin resistance, and adipocyte hypertrophy." (PMID 33167412, 2020). "Nevertheless, the mechanisms of NLRP3 inflammasome activation mediated by HFD and obesity are not fully understood." (PMID 28786950, 2017). "Conversely, in late obesity, after the establishment of leptin resistance at 16 wk of HFD feeding, the disruption of canonical and noncanonical leptin signalling leads to failure in NLRP3 inflammasome activation and M1 macrophage regulation." (PMID 38580672, 2024). "Consequently, we posit that alirocumab or statin administration holds promise in preventing lung fibrosis by suppressing pro-inflammatory cytokines, the RAS, the NLRP3 inflammasome, and subsequently, TGF-β1 signaling, independent of obesity." (PMID 38762465, 2024). "Although the exact activator or mechanism of the NLRP3 inflammasome is not known, it can be determined that MLFE normalizes the levels of the NLRP3 inflammasome and suppresses skin inflammatory responses during the early stages of wound healing in obesity." (PMID 35992142, 2022). "A high-fat diet induced increased LPS production by Gram-negative bacteria in the gut, while patients with obesity and T2DM were shown to lose weight and have increase insulin sensitivity and reduced NLRP3 and IL-1β expression after reducing their energy supply and exercising." (PMID 36232938, 2022).
Alzheimer disease (455 papers, 2010 to 2026). A progressive, neurodegenerative disease characterized by loss of function and death of nerve cells in several areas of the brain leading to loss of cognitive function such as memory and language. "One key mechanism involves activation of the NF-κB pathway and the NOD-like receptor family pyrin domain-containing 3 (NLRP3) inflammasome, both of which are strongly implicated in Alzheimer’s disease (AD) and related dementias." (PMID 41007636, 2025). "Neuroinflammation and microglial dysregulation are central features of many chronic neurodegenerative diseases, such as Alzheimer's disease and Parkinson's disease, where NLRP3-mediated pyroptosis has also been implicated." (PMID 41250673, 2025). "NLRP3 remains the most studied inflammasome and has been implicated in the pathogenesis of many diseases such as ad, PD and amyotrophic lateral sclerosis, but studies on its role in muscle disorders are limited." (PMID 39723571, 2025). "Neuroinflammation driven by microglial activation represents a pivotal pathological mechanism underlying brain injury in Alzheimer's disease (AD), with NLRP3 inflammasome activation being a hallmark feature of this process." (PMID 40357234, 2025). "Increasing evidence indicates that NLRP3 is a pivotal pathogenic driver across multiple neurodegenerative diseases, with demonstrated involvement in Alzheimer’s disease (AD), Parkinson’s disease (PD), and MS." (PMID 40830103, 2025). "Dysregulation of NLRP3 is closely associated with the pathogenesis of various inflammatory diseases, such as osteoarthritis (OA) and Alzheimer's disease (AD)." (PMID 41362453, 2025). "Aluminum induces inflammatory responses mediated by the activated NLRP3 inflammasome in bone, leading to severe bone loss, in the urticaria mouse model, and in the Alzheimer’s disease model." (PMID 41369395, 2025). "Aluminum has been reported to trigger inflammatory responses, which are mediated by NLRP3 inflammasome activation in bone, leading to severe bone loss, in the urticaria mouse model, and a model of Alzheimer’s diseases in the brain." (PMID 41369395, 2025). "Nonsteroidal anti-inflammatory drugs (NSAIDs) have shown potential in delaying the onset of Alzheimer’s disease (AD) or reducing its risk, likely through their modulation of the NLRP3 inflammasome pathway." (PMID 40260242, 2025). "The pathogenesis of Alzheimer's disease is closely linked to microglial involvement, as Aβ deposits induce the formation of NLRP3 inflammasome in microglia, leading to the maturation of interleukin-1β and triggering inflammatory responses." (PMID 38317229, 2024). "NLRP3 inflammasome activation has been implicated as a key neuroinflammatory pathway in Alzheimer’s disease, contributing to cognitive decline." (PMID 39201402, 2024). "Dysregulated NLRP3 inflammasome activation has been implicated in several central nervous system (CNS) disorders, including stroke, Alzheimer’s disease and Parkinson’s disease." (PMID 38327788, 2024). "The NLRP3 inflammasome has been implicated in the development of several neurological disorders, including Alzheimer’s disease and depression." (PMID 36280756, 2023). "The NLRP3 inflammasome is associated with various disorders such as liver disease, cancer, and Alzheimer’s disease." (PMID 37322517, 2023). "Neurological disorders such as Alzheimer’s disease, Parkinson’s disease, traumatic brain injury, stroke, depression, and multiple sclerosis are often associated with the progression of NLRP3 inflammatory vesicles." (PMID 38115996, 2023). "NLRP3 has been found to cause deficits in synaptic plasticity in animal models of Alzheimer’s disease." (PMID 36138986, 2022). "Complement has been implicated in several neuroinflammatory diseases including Alzheimer’s disease and linked with NLRP3 inflammasome activation." (PMID 35262626, 2022).
Alzheimer disease (continued). "Several inflammatory diseases such as Alzheimer's disease, Multiple sclerosis, and Traumatic brain injury are known to be associated with upregulation of NLRP3-inflammasome by the autophagy pathway." (PMID 35966798, 2022). "In a mouse model of Alzheimer’s disease, altered gut microbiota were associated with an increased NLRP3 inflammasome, enhanced astrogliosis and microglial activation." (PMID 35631301, 2022). "Recently, the activation of the pyrin domain-containing protein 3 (NLRP3) inflammasome has been found to be associated with various neurological disorders, such as Alzheimer’s disease, cerebrovascular disease and epilepsy." (PMID 35624482, 2022). "Enhanced NLRP3 inflammasome-mediated IL-1β secretion in microglia is associated with the progression of Alzheimer’s disease by reducing the phagocytosis of Aβ from microglia." (PMID 35514993, 2022). "It is known that microglial NOD-like receptor 3 (NLRP3) is associated with neuroinflammation and is also a therapeutic target in Alzheimer’s disease." (PMID 35741573, 2022). "More importantly, activation of the NLRP3 inflammasome is also associated with neurodegenerative diseases, such as Alzheimer’s disease (AD) and Parkinson’s disease (PD)." (PMID 35219323, 2022). "Primary microglia stimulation in vitro by fibrillar Aβ activates the production of NLRP3 inflammasome, caspase-1, causing the increased secretion of IL-1β in the animal models of Alzheimer’s disease." (PMID 36009120, 2022). "Recent studies demonstrated that NLRP3 inflammasome is involved in neurodegenerative diseases and NLRP3 deficiency plays a protective role in animal models of Alzheimer’s disease (AD) and PD." (PMID 34930303, 2021). "The NLRP3 cascade has been implicated in multiple diseases, such as Alzheimer’s disease, Parkinson’s disease, and stroke." (PMID 33402173, 2021). "Dysregulation of the NLRP3 inflammasome has been implicated in the progression of several neurodegenerative disorders, such as Alzheimer’s disease, Parkinson’s disease, Huntington’s disease, amyotrophic lateral sclerosis, and prion diseases." (PMID 33776778, 2021). "NLRP3 inflammasome activation has been linked to the development of multiple inflammatory diseases, such as atherosclerosis, type II diabetes, and Alzheimer’s disease, as well as various cancers." (PMID 33672982, 2021). "In an animal model of Alzheimer's disease, zinc deficiency worsened cognitive decline because of an enhancement in NLRP3-driven inflammation." (PMID 33597269, 2021). "A peculiar pattern of miRNA expression was suggested to characterize Alzheimer’s disease, a condition that is also associated with an excessive activation of the NLRP3 inflammasome." (PMID 34832969, 2021). "The NLRP3 inflammasome has an essential role in the deterioration caused by inflammation in Alzheimer’s disease and type 2 diabetes mellitus (T2DM)." (PMID 34769018, 2021). "Several researchers also used the same NLRP3-knockout strain as ours, which indicates that deficiency of NLRP3 also alleviates cognitive function impairments in Alzheimer's disease, Parkinson's disease and 24 h post-TBI." (PMID 34666797, 2021). "The NLRP3 inflammasome is implicated in a variety of human diseases including Alzheimer’s disease (AD), prion diseases, type 2 diabetes, and numerous infectious diseases." (PMID 32824985, 2020). "The inappropriate activation of the NLRP3 inflammasome has been implicated in several diseases, including Alzheimer’s disease, heart disease, and diabetes." (PMID 33216713, 2020). "Lysosomal destabilization was first revealed as a pathway mediating the activation of NLRP3 inflammasome by amyloid β, a pathogenic misfolded protein expressed in Alzheimer’s disease." (PMID 33603747, 2020). "Amyloid β (Aβ), a pathogenic misfolded protein expressed in Alzheimer’s disease, was first identified to activate NLRP3 inflammasome through lysosomal destabilization." (PMID 30755589, 2019).
Alzheimer disease (continued). "The NLRP3 inflammasome has been implicated in a wide range of diseases, including Alzheimer’s disease, Prion diseases, type 2 diabetes, and some infectious diseases." (PMID 30755589, 2019). "Previous studies have shown that there is an association between NLRP3 gene polymorphisms and susceptibilities to certain diseases, including Crohn's disease, abdominal aortic aneurysms, and late-onset Alzheimer's disease." (PMID 29850543, 2018). "NLRP3 inflammasome plays an important role in some chronic inflammation associated complex diseases, including T2D, Alzheimer’s disease, and atherosclerosis." (PMID 29959312, 2018). "TNF-α also has been associated with aseptic activation of inflammasome NLRP3 which mediates several major chronic diseases including arteriosclerosis, type 2 diabetes and Alzheimer disease." (PMID 29541394, 2018). "Canonical NLRP3 inflammasome activation is reported to be linked to inflammation-induced cognitive function decline in aging and Alzheimer’s disease." (PMID 29665808, 2018). "Emerging studies now focus heavily on understanding the mechanisms underlying NLRP3 activation in microglia in inflammation associated with neuropathology ranging from neurodegenerative diseases such as Alzheimer’s disease to psychiatric illnesses." (PMID 29941796, 2018). "NLRP3 inflammasome activity has been associated with Alzheimer’s disease, and recent reports, from our laboratory and others, indicate that Nlrp3 is required for neuroinflammation and nigral cell loss in animal models of PD." (PMID 30131971, 2018). "NLRP3-dependent secretion of IL-1β is closely linked to numerous non-communicable diseases including haemorrhagic disorders, Alzheimer’s disease, gout, diabetes and atherosclerosis." (PMID 28067797, 2017). "The in vivo relevance of the NLRP3 inflammasome in Alzheimer's disease has recently been demonstrated in the APP/PS1 mouse model where NLRP3-deficient mice show less severe disease symptoms." (PMID 26091541, 2015). "Upon activation, NLRP3 triggers the production of bioactive inflammatory cytokines and is pathogenic in complex diseases such as multiple sclerosis, type 2 diabetes, atherosclerosis, Alzheimer’s disease and many more disorders." (PMID 40643515, 2025). "Importantly, NLRP3 inflammasome-driven neuronal pyroptosis has been linked to the development of several neurodegenerative diseases, including Alzheimer’s disease (AD), traumatic brain injury (TBI), and Parkinson’s disease (PD)." (PMID 41002402, 2025). "NLRP3 inflammasome-dependent caspase-1 activation is an important pathway related to IL-1β release and has been implicated in the pathophysiology of neurological diseases, including Parkinson’s disease, Alzheimer’s disease, multiple sclerosis, and epilepsy." (PMID 38218765, 2024). "Acacetin also inhibits the expression of NLRP3 in cerebral ischemia-reperfusion injury, suppresses NLRP3 expression and enhances gp78-mediated NLRP3 ubiquitination in depression-associated dry eye disease, and reduces the expression of NLRP3 in mice with Alzheimer’s disease." (PMID 39459239, 2024). "Previous studies showed that the activation of the NLRP3 inflammasome is associated with the accumulation of α-synuclein aggregates, and these studies further confirmed the role of NLRP3 in amyloid β and tau driving in Alzheimer’s disease." (PMID 38125810, 2023). "Furthermore, besides inflammation, LCN2 was connected to neurodegenerative diseases, especially Alzheimer disease, while NLRP3 was associated with multiple sclerosis." (PMID 37240031, 2023). "NLRP3, one of the most investigated, is found in microglia and neurons in the brain and has been linked to neurogenesis, angiogenesis, neuroinflammation, and neuronal recovery in Alzheimer’s disease (AD), Parkinson’s disease (PD), and ischemic stroke." (PMID 37915409, 2023).
Alzheimer disease (continued). "IAPP is one of several disease-causing amyloids or misfolded proteins that activate the NLRP3 inflammasome, as for example amyloid β- and superoxide dismutase 1-induced inflammasome activation contribute to development of Alzheimer’s disease or amyotrophic lateral sclerosis, respectively." (PMID 37283747, 2023). "However, aberrant activation of the NLRP3 inflammasome has been linked with several inflammatory disorders: cryopyrin-associated periodic syndromes, Alzheimer’s disease, diabetes mellitus, prion diseases, and atherosclerosis." (PMID 37507744, 2023). "Mounting evidence has shown that the NLRP3 inflammasome can cause inflammatory reactions linked to several diseases of the nervous system, including cerebral hemorrhage, brain infarction, traumatic brain injury, Alzheimer’s disease, and encephalitis." (PMID 37371417, 2023). "The reduction of the cerebral glucose metabolism is closely related to the activation of the NOD-like receptor protein 3 (NLRP3) inflammasome in Alzheimer’s disease (AD); however, its underlying mechanism remains unclear." (PMID 36978970, 2023). "The right panel of the chart illustrates the major diseases associated with NLRP3 inflammasome, in addition to “alzheimers disease”, including “ischemic stroke”, “traumatic brain injury”, “multiple sclerosis”, “parkinsons disease”, “intracerebral hemorrhage” and “subarachnoid hemorrhage”." (PMID 36160384, 2022). "The NLR family pyrin domain containing 3 (NLRP3) inflammasome is a thoroughly studied inflammasome that is closely associated with Alzheimer’s disease, spinal cord injury, and other diseases and plays an important role in the diagnosis and treatment of human immune system diseases." (PMID 36337711, 2022). "Neuroinflammation is a common feature of neurodegenerative diseases such as Alzheimer’s disease, Parkinson’s disease, Huntington’s disease, and multiple sclerosis, and is associated with the activation of the NLRP3 inflammasome, which in turn leads to neurodegeneration." (PMID 36497196, 2022). "Specifically, the evidence from murine lung injury models by coronaviruses emphasizes the correlation between the NLRP3 inflammasome-mediated and the pathological accumulation of neurodegeneration-associated peptides such as fibrillar amyloid-β, leading to Alzheimer’s disease." (PMID 35625558, 2022). "Therefore, NLRP3/ASC/caspase-1 signaling pathways are implicated in the neuroinflammatory effects of Alzheimer’s disease." (PMID 36009120, 2022). "The NLRP3 inflammasome is a protein complex that promotes the release of inflammatory factors in response to infection or tissue injury and is known to be associated with many nervous system diseases, such as Alzheimer’s disease (AD), depression and epilepsy." (PMID 35624482, 2022). "However, dysregulation of the NLRP3 inflammasome activity causes many conditions, including Alzheimer’s disease." (PMID 34769018, 2021). "We report here that zinc supplementation in people reduced the prevalence and symptomatic decline of Alzheimer's disease, and that zinc deficiency in an Alzheimer's disease mouse model accelerated cognitive decline through potentiation of NLRP3-dependent inflammation, an effect that was reversible." (PMID 33597269, 2021). "NLRP3 inflammasomes is thus a vital player in innate immunity and inflammation, and its dysregulation has been implicated in a wide range of diseases, including Alzheimer’s disease, Prion diseases, type 2 diabetes and some infectious diseases." (PMID 33972672, 2021). "Among the inflammasomes, NATCH, LRR, and PYD domain-containing protein 3 (NLRP3) is well characterized and is associated with several human disorders such as Alzheimer's disease, obesity, rheumatoid arthritis, asthma, nonalcoholic fatty liver disease, and autoimmune encephalitis." (PMID 33613822, 2021).